CXCL10 (C-X-C motif chemokine ligand 10)
Diseases named in the same sentence as CXCL10 in open-access papers (continued):
Sharing a sentence is not in itself a finding about the gene and the disease.
infection (continued). "In fact, TNF-α acts synergistically with IFN-γ to stimulate the production of nitric oxide (NO) by macrophages and influences the expression of chemokines, such as CCL5, CCL9, CXCL10, and CCL2, which induce migration to and maintenance of immune cells in the infection site." (PMID 28659665, 2017). "Thus, inflammation in the form of Cxcl10 is mounted as early as 1 DPI in the TG, its divisions, and the OB further indicating that infection has occurred at this early time point." (PMID 28645309, 2017). "MuV significantly increased CXCL10 levels in the media of both WT and TNF-α−/− cells; however, the CXCL10 level in TNF-α−/− cells was significantly lower than that in WT cells in response to MuV infection." (PMID 29072682, 2017). "CXCR3 and its ligands, CXCL9, CXCL10, and CXCL11, play a pivotal role in the regulation of inflammatory and infectious diseases, in which CXCR3-bearing effector leukocytes are recruited to the sites of inflammation or infection." (PMID 27068264, 2016). "The same pattern was observed for CXCL10 (age: p<0.001, infection: p=0.609, infection*time: p =0.684), CXCL1 (age: p<0.001, infection: p=0.865, infection*time: p =0.121), and CCL2 (age: p<0.001, infection: p=0.921, infection*time: p =0.263)." (PMID 26856410, 2016). "During acute infection with L. interrogans serovar Icterohaemorrhagiae, hamsters upregulate gene expression of TNF-α, TGF-β, IP-10 (CXCL10), and IL-10 at the site of infection (kidney) and peripheral blood mononuclear cells upregulate expression of TNF-α, IFN-γ, IL-12." (PMID 27486445, 2016). "Cxcl10 is upregulated in response to interferons, however Ifna, Ifnb, and Ifng transcription was very low or absent in KC and IM at any time point during infection." (PMID 27812182, 2016). "Neither pre-infection CXCL10 nor MX1 transcript levels correlated with overall early plasma viral load." (PMID 27902344, 2016). "Through induction of IL-6 as well as chemokines such as CCL2, CXCL8, and CXCL10, Vγ9/Vδ2 T cells and MAIT cells are likely to enhance local inflammation and contribute to further recruitment of monocytes, neutrophils, and lymphocytes to the site of infection." (PMID 27527598, 2016). "Furthermore, another group reported that the CXCR3 ligands, CXCL9, CXCL10 and CXCL11, were induced markedly at the levels in the spleen, lung, and liver following infection with T. gondii." (PMID 24661782, 2014). "TgCyp18 may also play a role with CCL5 in the migration of macrophages to the site of infection, and with CCL2 and CXCL10 in the transport of T. gondii-infected cells to the liver." (PMID 24661782, 2014). "Additionally, neutrophils recruited to the site of infection produce numerous cytokines and chemokines, including CXCL9, CXCL10 and CXCL11." (PMID 24646914, 2014). "It has been shown that lack of CXCL9 and CXCL10 significantly alters the ability of the host to control genital HSV-2 infection through the mobilization of effector cells to sites of infection." (PMID 23922974, 2013). "CXCL13 appears redundant, as infection of CXCL13-deficient mice does not affect CNS accumulation of CD19+ B cells, leaving CXCL10 as a likely candidate to recruit SINV-specific ASC to the CNS." (PMID 23435240, 2013). "Following infection by C. parvum sporozoites in vitro, the mouse epithelial cell line CMT-93 upregulated CXCL9 and CXCL10 24 h later suggesting that independently of IFNγ, IEC can in some conditions upregulate these chemokines in direct response to the parasite." (PMID 24367259, 2013). "Similar to CXCL10, both BAFF and APRIL localize predominantly to astrocytes, enforcing their prominent role in recruitment, as well as their maintenance of ASC during MHV-JHM infection." (PMID 23435240, 2013).
infection (continued). "Mindful that the expression of chemokines and cytokines in the serum does not allow the localization of chemokine/cytokine producing cells, we used quantitative RT-PCR to determine the relative expression of Ifng, CXCL10, CCL2 and CLL7 in spleen versus BM during infection with P. chabaudi." (PMID 23762028, 2013). "However, our findings with IFNγ−/− neonatal mice show that during the infection CXCL9 and CXCL10 upregulation was strongly IFNγ-dependent." (PMID 24367259, 2013). "Accordingly, IEC isolated from IFNγ−/− neonatal mice did not significantly upregulate the expression of CXCL9 and CXCL10 during the infection whereas other chemokines such as CCL3, CCL4 and CCL5 were still upregulated." (PMID 24367259, 2013). "Although TKO mDC failed to induce Ifnb expression after WNV-NY infection, they retained the ability to respond to its signaling, inducing WT levels of Ifnb, Oas1a, Rsad2, and Cxcl10 at 24 hours after IFN-β treatment." (PMID 23300459, 2013). "Furthermore, the authors found that CXCL10 and IFN-β expression was dependent on DDX60 during infection with HSV-1 and VSV in an endothelial cells line." (PMID 23435233, 2013). "Very recent data has shown that infection with enveloped viruses may trigger virus–cell fusion events inducing innate signaling via the adaptor protein STING, including CXCL10 expression." (PMID 23435233, 2013). "Furthermore the increase in levels of CXCL10 and CCL7 occurred subsequently to the infection-induced upregulation of IFN-γ, since peak levels for this cytokine were reached in C57BL/6 mice 2–3 days earlier." (PMID 23762028, 2013). "It is intriguing that astrocytes are rarely infected by MHV-JHM suggesting their CXCL10 expression is driven by T cell-derived IFN-γ rather than infection itself." (PMID 23435240, 2013). "We later showed that immunization with L. intermedia SGS altered the course of experimental infection with L. braziliensis and stimulation of immune mice with a combination of SGS and L. braziliensis led to a decreased CXCL10 expression and increased IL-10 expression." (PMID 23284976, 2012). "On the other hand, in parallel with the gene expression profile, influenza H5N1 virus elicited more IP-10 (CXCL-10) secretion in BMDMΦ than mock (p = 0.001), influenza H1N1 (54/98) (p = 0.05) and WSN/33 virus infected cells (p = 0.05) after 24 hours post-infection." (PMID 23226456, 2012). "Moreover, CXCL10 binds CXCR3 and enrolls Th1 cells to resist intracellular pathogen infection, such as viruses." (PMID 22906315, 2012). "For example, the viral protein ICP27 appears to harbor immune-modulatory capabilities, as demonstrated by more potent stimulation of CXCL10 and other cytokines in macrophages infected with a HSV-1 ICP27-deletion mutant compared with infection with wild type virus." (PMID 23062757, 2012). "HSV-1 DNA released during early infection may be recognized by IFI16, resulting in expression of CCL3; while, CXCL10 expression is mediated via an IFI16-independent pathway." (PMID 23062757, 2012). "Increased expression of CXCL9, CXCL10, and CXCL11 suggests either that IFN-γ induces the expression of these chemokines or that Type I interferons are increased during the first 12 hours of infection in the bovine intestine." (PMID 22096503, 2011). "Similarly, at 18 hours post-H9N2/1997 infection, CCL-5/RANTES mRNA expression was found to be induced by nearly 1000 folds; while CXCL-10/IP-10, IL-6, and IL-8 were found to be up-regulated by 16-116 folds." (PMID 21108843, 2010). "At the late phase of infection; induction of IL-8, CCL-5/RANTES, and CXCL-10/IP-10 occurred." (PMID 21108843, 2010). "Similarly for H9N2/1997 infection, there was 5-25 folds increase in the transcription of CCL-5/RANTES, TNF-α, and CXCL-10/IP-10 mRNA at 3 hours post-infection." (PMID 21108843, 2010).
infection (continued). "Moreover, Tbk1−/− MEF show marked defects in type I IFNs, Cxcl10, and RANTES gene expression after infection with either Sendai or Newcastle disease viruses or after engagement of the TLR3 and TLR4 by double-stranded RNA and LPS, respectively." (PMID 20090833, 2010). "In general, H5N1/2004 showed a higher capacity in inducing CXCL-10/IP-10 and CCL-5/RANTES as compared with that of H1N1 and H9N2; and the effects were more prominent at the late phase of infection, particularly at 24 hours post-infection." (PMID 21108843, 2010). "Cytokines - CXCL10 and RANTES were up-regulated by 4 and 2 folds respectively in WB-NIV2664 infected cells but were down-regulated by 3 and 2 folds respectively in response to infection with IBCDC-RG7." (PMID 20828378, 2010). "CXCL-10 initiates its biological functions through binding to its high affinity receptor CXCR-3 leading to recruitment of the activated effector lymphocytes including CD4+ and CD8+ T cells as well as NK cells to the site of infection or injury." (PMID 19442267, 2009). "Administration of neutralizing anti-CXCL10 antibodies at an earlier (i.e. before infection) or later (i.e. 7 days post-infection) time failed to interfere with the autodestructive process." (PMID 23675028, 2007). "A comparative study using Plasmodium berghei ANKA infected C57BL/6 and BALB/c mice indicated th at both strains of mice expressed CXCL10 (interferon-induced protein 10, IP-10) and CCL2 (monocyte chemotactic protein-1, MCP-1) chemokine genes as early as 24 hours post-infection." (PMID 16359553, 2005). "Notably, levels of circulating human CXCL10 in persistently infected CD4 + cell-depleted mice were not statistically different than those of mice that resolved infection (12 dpi)." (PMID 40920821, 2025). "Interestingly, in contrast to our previous studies, there was no vaccine-mediated reduction in the local levels of infection-induced CXCL10 and CXCL11 levels in BAL fluid in any of the treated groups." (PMID 41390777, 2025). "Given that CXCL10 serves as a chemoattractant for recruiting immune cells to infected neurons, it is most likely crucial for control of infection regardless of pathogen, which further warrants validation of neuronal CXCL10 and its role in mediating the control and clearance of CNS pathogens." (PMID 40762468, 2025). "To find out whether a decrease of virus load observed in the presence of Iristatin results in a decrease of IFN or ISGs, we measured gene expression of IFN-β and four interferon-stimulated genes, namely ISG15, CXCL-10, OASL2, and IFIT2 in skin tissue two and 5 days after Hypr infection." (PMID 39821815, 2025). "Additionally, severe influenza virus infection was associated with hypercytokinemia, including increased cytokine (IFNβ, TNF, IL-10 and IL-12p70) and chemokine (MCP-1 (CCL2), KC (CXCL1), IP-10 (CXCL10) and RANTES (CCL5)) levels in the severe infection group at 7 dpi." (PMID 41285788, 2025). "In addition, the expression of Ifnb1 and Cxcl10 was severely impaired, whereas EMCV replication was exacerbated in the brains or lungs of Lyz2‐Cre Usp8fl/fl mice compared with control littermates 48 h after EMCV infection." (PMID 40525588, 2025). "For instance, genomic and epigenomic profiling of COVID-19 survivors has revealed persistent open chromatin states at IL-1β, TNF, and CXCL10 loci, marked by sustained H3K4me3 and H3K27ac, supporting continued cytokine expression even in the absence of active infection." (PMID 40969755, 2025). "In addition, the expression of CCL2, CXCL10 and IL-6 represented a non-significant difference with the infection of SC16, HN10 and CVS-11." (PMID 39273091, 2024). "However, by 12 hours after infection, the expression of Ccl2, Cxcl1, Cxcl9, and Cxcl10 in the dLN of WT CHIKV–infected WT mice, but not MARCO–/– mice, was significantly increased in comparison with mock-infected mice." (PMID 38194268, 2024).
infection (continued). "Intriguingly, while UL138 expression reduced IFNB1 and CXCL10 accumulation downstream of cGAS-STING-TBK1, it has also been reported to enhance the expression of some interferon stimulated genes (ISGs) at late times during productive infection, presumably by promoting the activation of STAT1." (PMID 38932169, 2024). "During the acute febrile phase of infection, patients with DHF and DWC exhibitedelevated CXCL-8 (p-value < 0.01) comparedwith those with DF.Furthermore, patients with DHF and DWC exhibited increased CXCL-10 serum levels(p-value < 0.01) compared to those with DF." (PMID 39082520, 2024). "Furthermore, our findings indicate highly activated CXCL10 in neutrophils challenged with S. aureus challenge in vitro, consistent with previous studies observing elevated CXCL10 and CXCR3 in neutrophils during infection with Salmonella, Aspergillus, or respiratory virus." (PMID 39001897, 2024). "Similarly, the chemokines CCL2 (attracting monocytes), CXCL2 (attracting neutrophils), CCL5 (attracting T cells), CXCL10 (attracting activated T cells, eosinophils), and CCL11 (eosinophils) were elevated during infection with a significant reduction in TLR7 KO mice." (PMID 39769461, 2024). "Furthermore, only infection with Omicron resulted in a significant induction of Ifna5 and Ifnb, ISG-driven antiviral effectors Mx1, Oas1, and Viperin, and pro-inflammatory mediators Cxcl10 and Il6." (PMID 38742107, 2024). "Notably, we again observed that WY14643 reduced the transcripts of Ifnb, Isg15, Isg20, and Cxcl10 without infection, though the effect was not significant for Isg20 in Ppara−/− cells." (PMID 36715509, 2023). "Interestingly only Mayotte 2008 induced an increased secretion of IFN-β, CXCL9, CXCL10, and CCL5, and only CXCL11 was increased for both RVFV strains infection." (PMID 37306630, 2023). "Similarly, the consistent overlapping expression of the CXCR3 ligands, Cxcl9, Cxcl10 and Cxcl11 may also be unsurprising as there will be distinct stages of the immune response where CXCR3+ T cells are required to fight infection/disease." (PMID 37934811, 2023). "Interestingly, CXCL10, which was not spontaneously expressed and not induced by infection, showed considerably less interferon-induced expression in RH and Me49 infected cells." (PMID 37205102, 2023). "Although it is possible that CXCL-10 can be elaborated in the skin in the absence of obvious inflammation, elevations of Galectin-9 are not reported to occur in this setting and are typically seen when there is chronic inflammation or infection." (PMID 36765391, 2023). "Ex vivo production of CXCL-10 in whole blood cultures stimulated with a canonical viral antigen poly-IC was somewhat increased on d-1 (prior to RV16 infection) compared to d-55 (NS) and was significantly higher on the first days after infection in both cRG-I groups." (PMID 36296939, 2022). "Therefore, the question of whether infection of endothelial cells by SARS-CoV-2 induces the epigenetic reprogramming of p63 activation in pulmonary tissues, leading to CXCL10 expression and FasL expression, deserves to be further addressed." (PMID 35066575, 2022). "Concomitantly to autophagy activation in MERS-CoV-MA-Δ4b infection, a significant decrease in the pro-inflammatory response was observed in MRC5 cells, including the expression of IFN-ß, NF-kB dependent cytokines (IL-6 and IL-8) and chemokines (CCL2 and CXCL10)." (PMID 36129908, 2022). "The CXCL9, CXCL10, CXCL11/CXCR3 axis and TNFSF13B play a role in both these recruitment and activation processes, responsible for attracting Th1 cells, cytotoxic lymphocytes and natural killer cells to the site of the infection, and related to B-cell activation, respectively." (PMID 34276658, 2021). "In the context of CXCL10 and BST2 roles during liver fluke infection, they may participate in the host defense mechanism such as the immune response at the early stage of the infection." (PMID 33879231, 2021).
infection (continued). "This highlighted that CXCL10 and CXCL11, chemokines responsible for immune cell recruitment to the site of infection from the bloodstream, were among the core group of 29 DE genes and could be detected at both temperatures, albeit up-regulation was stronger at 37°C compared to 33°C." (PMID 33780434, 2021). "A positive correlation between MIG/CXCL9, IP-10/CXCL10, I-TAC/CXCL11 and MIP-3β/CCL19 and mononuclear cell infiltrates was also observed in previous studies on TBE patients, confirming their potential involvement in lymphocyte extravasation to the site of infection during TBE." (PMID 34277474, 2021). "Some of the genes that were similarly modulated by MR766 and Rio-U1 related to cytokine signaling (CXCL10/11, CCL8) and the IFN response (IFIT2, ISG15, OAS2, DDX58, among others), suggesting some degree of similarity in signaling patterns following infection with either virus." (PMID 33405202, 2021). "In recognition of the ability of SARS-CoV-2 to induce an inflammatory response following infection of intestinal cells, we used Caco-2 cells to test the ability of spike protein RBD and heat-inactivated SARS-CoV-2 to activate NF-kappaB and induce secretion of IFN-γ and CXCL10." (PMID 34741071, 2021). "Although it is not well understood if NF-κB and STAT3 are activated during HTLV-1 de novo infection, we speculate that NF-κB and STAT3 are activated, as NF-κB and STAT3-regulated inflammatory molecules, including IFN-γ, IL-1, TNF-α, IL-6 and CXCL10, are produced during HTLV-1 de novo infection." (PMID 33182552, 2020). "This suppression appeared to occur only late during infection, beginning at 72 h and being nearly complete by 96 h, consistent with release of CPAF during host-cell lysis, though the mechanism of suppression of CXCL10 requires further biochemical investigation." (PMID 33106516, 2020). "Our results demonstrated that vaccination with pcHrp1 or pcHrp1+pcIL-34 could significantly trigger the expression of IL-8, CCL2, CXCL9, CXCL10, and CCL20, indicating that the chemokines were involved in the recruitment of neutrophils, monocytes, Th1 cells, and Th17 cells to the infection sites." (PMID 32231137, 2020). "CXCL10 expression could be observed in the beta cells of donors with recent-onset T1D, irrespective of their infection status with enterovirus." (PMID 33469446, 2020). "Infection of PMA‐treated THP‐1 shSAMHD1 cells with HIV‐1 GFP that had been produced in the presence of increasing doses of LPV led to a virus and LPV dose‐dependent increase in the expression of ISGs CXCL‐10, IFIT‐2 and MxA at the mRNA level, and CXCL‐10 protein secretion." (PMID 32852081, 2020). "Furthermore, virus produced in the presence of 30 and 100 nM LPV induced the expression of CXCL‐10 on infection of primary MDM, whereas virus grown in the absence of LPV, or at low LPV concentrations (10 nM), induced very little CXCL‐10 expression." (PMID 32852081, 2020). "Notably, the abundance of seven chemokines, such as C–C motif chemokine ligand 14 (CCL14), CCL20, CCL25, CCL5, C–X–C motif chemokine ligand 10 (CXCL10), CXCL14, and atypical chemokine receptor 3 (ACKR3), was significantly higher by infection in the R line of the TSF flock." (PMID 30678719, 2019). "Thus, CXCL10 and G-CSF were the earliest and most robustly upregulated chemokines in the serum of TBEV-infected animals, with elevation detectable starting at the viremic phase of infection." (PMID 31699097, 2019). "During these stages of infection, little or no virus could be detected in the brain; thus, the elevated CXCL10 in the brain at this time was likely of peripheral origin." (PMID 31699097, 2019). "These related proteases may suppress CXCL10 during different stages of infection or cleave an additional set of host substrates, even though they are not required for CXCL10 cleavage under our in vitro conditions." (PMID 31440475, 2019).